HIF1A (hypoxia inducible factor 1 subunit alpha)
Diseases named in the same sentence as HIF1A in open-access papers (continued):
Sharing a sentence is not in itself a finding about the gene and the disease.
pancreatic cancer (continued). "In conclusion, our study showed that c-Myc could promote the development of pancreatic cancer, and c-Myc downregulation could synergistically enhance the antitumor activity of bufalin by downregulating the HIF-1α/SDF-1/CXCR4 pathway." (PMID 32362830, 2020). "Besides, HIF-1α-mediated autophagy reduced lumican level secreted by pancreatic stellate cells, promoting pancreatic cancer progression." (PMID 32587480, 2020). "Therefore, the predominant downregulation of ENST00000480739 in pancreatic cancer favors HIF-1α activation and promotes pancreatic cancer invasion as demonstrated in vitro and in vivo." (PMID 32640630, 2020). "Similarly, several studies confirmed that HIF-1α increased expression of glycolytic-related enzymes and the production of lactic acid, meeting the metabolic needs of pancreatic cancer cells." (PMID 32587480, 2020). "Pancreatic cancer possesses hypoxic niche and is accompanied by HIF-1α overexpression." (PMID 32587480, 2020). "Nevertheless, the roles of HIF-1α in the apoptosis of pancreatic cancer cells remain controversial." (PMID 32587480, 2020). "Besides, lncRNA-FEZF1-AS1 enhanced pancreatic cancer cells proliferation via the miR-142/HIF-1α axis in hypoxia." (PMID 32587480, 2020). "In pancreatic cancer, HIF-1α bound to the HRE of lncRNA-NUTF2P3-001, upregulating its expression." (PMID 32587480, 2020). "HIF-1α manipulates the malignant biological features of pancreatic cancer through various pathways." (PMID 32587480, 2020). "Efficacy of HIF-1α inhibition was also demonstrated in orthotopic pancreatic cancer model." (PMID 30959799, 2019). "Our results demonstrated that PRMT5 could regulate aerobic glycolysis in pancreatic cancer via cMyc instead of HIF1α." (PMID 30922330, 2019). "Similarly, polymer–lipid nanoparticles have been used to deliver HIF-1α siRNA and gemcitabine to treat pancreatic cancers." (PMID 30959799, 2019). "It reflected that HIF-1α could be used to evaluate the survival time of patients with pancreatic cancer after diagnosis." (PMID 31711497, 2019). "The present study may shed light on approaches to prevent chemotherapy and radiotherapy resistance in pancreatic cancer by targeting the RAD51/HIF1α axis." (PMID 31889908, 2019). "Moreover, Rad51 positively regulates aerobic glycolysis in pancreatic cancer cells by regulating HIF1α protein stability and the HIF1α-targeted transcriptional program." (PMID 31889908, 2019). "Moreover, quantitative data emphasized the significance of HIF-1α in the prognostic evaluation of pancreatic cancer." (PMID 31711497, 2019). "Our results showed that hyperglycemia could induce hypoxia and increase the expression of HIF-1α in the normal pancreas and in pancreatic cancer." (PMID 30455857, 2018). "In addition, another study revealed that hypoxia activated HIF-1α expression, which subsequently led to upregulated of Hh signaling, and finally made pancreatic cancer more aggressive and resistant to treatment." (PMID 30081498, 2018). "Inhibition of HIF-1α by siRNA reversed the effect of high glucose on pancreatic cancer cells." (PMID 30455857, 2018). "Managing hyperglycemia-induced HIF-1α might be a novel strategy for the treatment of pancreatic cancer." (PMID 30455857, 2018). "Pancreatic cancer always exhibits an increased accumulation of stromal tissue with the features of desmoplasia and hypoxia, which lead to the stabilization of hypoxia inducible factor-1a (HIF-1α), the master regulator of glucose metabolism." (PMID 29476053, 2018). "Hence, targeting the mTORC2 component RICTOR decreases hypoxia-driven HIF-1α expression in pancreatic cancer cell lines and potentially affects factors that are influenced by this transcription factor." (PMID 28445935, 2017).
pancreatic cancer (continued). "Taken collectively, the data suggest that HIF1-α mediates activation of BNIP3 under hypoxic conditions that results in the induction of the mitochondrial pathway of apoptosis in pancreatic cancer cells, via the modulation of the expression of the proteins Bax, AIF and Bcl-2." (PMID 28968982, 2017). "In summary, it was identified that through targeting HIF-1α, pancreatic cancer cell proliferation and invasion are inhibited by miR-142; miR-142/ HIF-1α axis regulates hypoxia-induced cell proliferation and invasion through regulation of E-cad, vimentin and VEGF-C." (PMID 28069592, 2017). "In addition, 42 pancreatic cancer cases were analyzed, and the expression of HIF-1α and miR-142 was correlated with the stage of pancreatic cancer, and miR-142 was correlated with lymphatic metastasis." (PMID 28069592, 2017). "siRNA-mediated knockdown of HIF-2α, but not HIF-1α, increased susceptibility of two pancreatic cancer cell lines, Panc-1 and AsPC-1, to TRAIL in vitro under normoxic and hypoxic conditions." (PMID 28476028, 2017). "It is important to note that the contribution of additional transcription factors may be involved in the transcriptional activation of BNIP3 by HIF-1α in pancreatic cancer cells, as earlier noted for other types of cancers." (PMID 28968982, 2017). "We undertook the present study to investigate whether emodin and rhein from Rheum palmatum inhibited HIF-1α expression in human pancreatic cancer cells." (PMID 29152137, 2017). "The functional interference of SIM2s with the activity of HIF1α on BNIP3 may be involved in the hypoxic regulation of BNIP3 in pancreatic cancer cells, although further studies are required to confirm this hypothesis." (PMID 28968982, 2017). "In the present study, we investigated whether two components of Rheum palmatum, emodin and rhein, inhibited HIF-1α expression in human pancreatic cancer cells and whether the inhibiting effect, if any, attenuated cancer cachexia." (PMID 29152137, 2017). "Moreover, in surgical pancreatic cancer samples, the expressional level of HIF-1α significantly increased, and inversely correlated with miR-142 expression." (PMID 28069592, 2017). "Specifically, the present study further reveals that lncRNA-NUTF2P3-001 is upregulated in pancreatic cancer cells under hypoxia and CoCl2 treatment, which is attributed to the binding of hypoxia-inducible factor-1α (HIF-1α) to hypoxia response elements (HREs) in the upstream of KRAS promoter." (PMID 26755660, 2016). "HIF-1α knockdown abrogates the effects of NNK on pancreatic cancer proliferation and invasion." (PMID 26497365, 2016). "Therefore, all of these data intensively suggests that lncRNA-NUTF2P3-001 is transcriptionally regulated by HIF-1α in hypoxia of pancreatic cancer." (PMID 26755660, 2016). "In line with this, we could show that ectopic expression of p65/RelA in pancreatic cancer cells results in augmented HIF-1α accumulation and promoter activity already in normoxic condition." (PMID 26739387, 2016). "Next, we investigated whether HIF-1α contributes to NNK-induced pancreatic cancer proliferation and invasion." (PMID 26497365, 2016). "Therefore, it appears that pancreatic cancer cells that increase DUOX protein expression in response to IFN-γ up-regulate HIF-1α protein." (PMID 27637085, 2016). "Taken together, β2-AR signaling and HIF-1α may represent promising therapeutic targets for preventing smoking induced pancreatic cancer progression." (PMID 26497365, 2016). "Thus, our data indicate that β2-AR signaling regulates NNK-induced pancreatic cancer progression via upregulation of HIF-1α." (PMID 26497365, 2016). "NNK increases HIF-1α expression in pancreatic cancer in vitro and in vivo." (PMID 26497365, 2016).
pancreatic cancer (continued). "In pancreatic cancer cells, apoptotic resistance is modulated not only by Nox-generated ROS but also by hypoxia-inducible factor-1α [HIF-1α], a redox-sensitive transcription factor that is overexpressed in pancreatic carcinoma relative to adjacent normal pancreatic tissue." (PMID 27637085, 2016). "In addition to the adverse consequences of elevated VEGF-A levels in pancreatic cancer, abundant expression of HIF-1α contributes substantially to the pathophysiology of this disease." (PMID 27637085, 2016). "Similarly, expression of HIF-1α protein was found in pancreatic cancer cells and cholangiocarcinoma cells under normoxia." (PMID 26393682, 2015). "In this regard, pancreatic cancer cell lines that constitutively express HIF-1α are more resistant to apoptosis induced by hypoxia compared to similar cell lines that lack constitutive expression of HIF-1α." (PMID 26002039, 2015). "While PCNA is a marker of cellular proliferation, HIF1α has been shown to be associated with negative prognosis of several cancers including pancreatic cancer." (PMID 25929337, 2015). "Cancer therapy using an anti-VEGF Ab upregulated CXCR4 in rectal cancer cells, and upregulation of CXCR4 and increased invasiveness mediated by reactive oxygen species, NF-κB, and HIF-1α was observed in pancreatic cancer cells treated by the chemotherapeutic agent gemcitabine." (PMID 26083776, 2015). "However, high concentrations of HIF-1α resulting from activation of the phosphoinositide 3-kinase/Akt pathway have been reported to potentiate resistance to hypoxia-induced apoptosis in a pancreatic cancer cell line." (PMID 26017562, 2015). "Moreover, the presence of an autocrine signaling loop between HIF-1a and STAT-3 was demonstrated in pancreatic cancer cell lines, where hypoxia mediates an increase in IL-6 production through HIF-1a leading to activation of STAT-3." (PMID 26517240, 2015). "In summary, this study demonstrates that RAGE expression is regulated by a NF-κB-dependent pathway and the upregulated binding of RAGE to mutant KRAS facilitates HIF1α activation in a range of pancreatic tumor cells, as well as a spontaneous pancreatic tumor model in transgenic mice." (PMID 25341034, 2014). "Recent studies reported that CsA might enhance the chemotherapeutic effect of cytotoxic agents in various cancers, whereas HIF-1α knockdown might increase chemo-sensitivity in pancreatic cancer cell line." (PMID 24662981, 2014). "Hypoxia induces NF-κB-dependent and HIF1α-independent RAGE expression in pancreatic tumor cells." (PMID 25341034, 2014). "In this regard, HIF-1α is up-regulated in PDACs and can play critical roles for the adaptation of pancreatic cancer cells and stromal cells to the hypoxic desmoplastic microenvironment during disease progression, treatment resistance and a poor outcome for PDAC patients." (PMID 23301832, 2013). "We first explored the expression of GLI1 and HIF-1α in six human pancreatic cancer cell lines." (PMID 23786654, 2013). "Several experimental studies have shown that the hypoxia-induced miR-210 increases the expression of hypoxia-induced downstream targets VEGF and CAIX (carbonic anhydrase 9) in pancreatic cancer cells by a HIF-1α-dependent mechanism, suggesting a regulatory role in tumor angiogenesis." (PMID 22952749, 2012). "Our data revealed that MUC17 was significantly induced by hypoxic stimulation through a hypoxia-inducible factor 1α (HIF1α)-dependent pathway in some pancreatic cancer cells (e.g., AsPC1), whereas other pancreatic cancer cells (e.g., BxPC3) exhibited little response to hypoxia." (PMID 22970168, 2012). "Hence, HIF-1α and CX3CR1 expression is strongly associated with more PNI in pancreatic cancer patients." (PMID 22952674, 2012). "Hence, HIF-1α inhibitors appear potentially and clinically relevant enhancers of pancreatic cancer radiosensitivity." (PMID 24281221, 2010).
pancreatic cancer (continued). "Based on these findings, we hypothesize that the hypoxic microenvironment in pancreatic cancer activates the TGF-β1/Smad signaling pathway via HIF-1α, thereby synergistically promoting the expression of ECM proteins (e.g., collagen I/III/V) and exacerbating tumor invasion and stromal fibrosis." (PMID 40406267, 2025). "Cellular adaptation to hypoxia is triggered by overexpression of HIF-1α via modulation of different signaling pathways to increase blood vessels formation, aggressiveness, metastasis, and resistance to treatments in numerous cancer types, such as breast, colorectal and pancreas cancer." (PMID 36776312, 2023). "Hence, HIF-1α signaling regulation may be a promising strategy for decreasing the malignancy of pancreatic cancer." (PMID 37763649, 2023). "Increased expression of HIF-1A, gene encoding hypoxia-inducible factor-1 alpha, the master regulator of oxygen sensing and metabolic regulation in cells, and INS encoding insulin further indicate that fibroblasts assume a pro-metastatic role and are complicit in pancreatic cancer progression." (PMID 35565326, 2022). "Therefore, a redox-sensitive nanoplatform co-delivering GEM and miR-159c was developed, which downregulates HIF-1α and genes responsible for glucose uptake and cancer cell metabolism, thereby significantly inhibiting orthotopic desmoplastic pancreatic cancer growth in NSG mice." (PMID 33672261, 2021). "Furthermore, it has been demonstrated that the knockout of HIF-1α gene in pancreatic cancer cells may result in the more invasive form of cancerous cell growth." (PMID 34207699, 2021). "Exploring whether hypoxia and Hif-1α activation exist stably in CP and the relationship between them and PSCs will help uncover the mechanism of transformation from chronic pancreatitis to pancreatic cancer." (PMID 34540683, 2021). "In pancreatic cancer, HIF-1α expression has been reported to be upregulated, and it is involved in the regulation of the Warburg effect, cancer metastasis and chemoresistance; upregulated expression of HIF-1α is associated with unfavorable prognosis of the patients." (PMID 34036383, 2021). "The direct interaction of epigenetic modifying enzymes with HIF-1α already points to a connection of hypoxic cell response and epigenetics and was strategic starting point for the following review about epigenetic regulation in dependence of hypoxia in pancreatic cancer." (PMID 33113836, 2020). "HIF-1α could inhibit E-cadherin expression via recruiting metastasis-associated protein 2 (MTA2)/HDAC1 complex to bind to E-cadherin promoter, inducing EMT in pancreatic cancer cells." (PMID 32587480, 2020). "Hence, targeting HIF-1α and its signaling pathways could be potential therapeutics for pancreatic cancer." (PMID 32587480, 2020). "Indeed, our results indicated that H-1-2 could inhibit AGR2 and HIF1α expression in pancreatic cancer both in vitro and in vivo." (PMID 32322663, 2020). "Therefore, targeting HIF-1α and its signaling pathways might be effective therapeutic approaches for pancreatic cancer." (PMID 32587480, 2020). "Besides, extracellular superoxide dismutase could accelerate the degradation of HIF-1α via reducing peroxides in pancreatic cancer." (PMID 32587480, 2020). "Therefore, the results suggested that these coexpressed genes might play an important synergistic role with P4HA1 in the progression of pancreatic cancer through glycolysis, HIF-1α, and metabolism." (PMID 33415167, 2020).
pancreatic cancer (continued). "Similarly, the antitumor effect of a novel synthetic derivative of curcumin treatment seen in pancreatic cancer was partially attributed to its inhibition of the expression of miR-21, miR-210, and HIF-1α, which are aberrantly upregulated under hypoxic conditions." (PMID 32014012, 2020). "Moreover, the HIF-1α/SDF-1/CXCR4 signaling pathway may be a potential therapeutic target for pancreatic cancer." (PMID 32362830, 2020). "Since ERO1α enzyme activity is known to generate reactive oxygen species (ROS) which directly regulate the hypoxia response through transcription factor HIF-1α, we next assessed whether ROS generation might underpin the influence of ERO1α on pancreatic cancer progression." (PMID 31666928, 2019). "Given that HIF-1α expression is known to be controlled by reactive oxygen species (ROS), we next assessed whether the generation of these mediators might represent an important mechanism by which ERO1α influences pancreatic cancer progression." (PMID 31666928, 2019). "HIF-1α plays a central role in these processes, and thus becomes the potential anticancer target of concern; however, whether HIF-1α is involved in the regulation of pancreatic cancer proliferation and invasion under hypoxia microenvironment still remained unclear." (PMID 28069592, 2017). "MUC1 may have an important role in disc aging and degeneration by acting as a regulator in the hypoxic environment, helping disc cells to survive under hypoxic conditions by stabilization and by activation of HIF-1α as previously recognized in pancreatic cancer cells." (PMID 28482827, 2017). "However, the function of BNIP3 and the mechanism of the association of HIF-1α with the BNIP3 promoter in pancreatic cancer cells have not yet been fully elucidated." (PMID 28968982, 2017). "Multiple pathways associated with aggressive biological behaviors in pancreatic cancer were enriched, including FoxO signaling pathway, mTOR signaling pathway, PI3K-Akt signaling pathway, AMPK signaling pathway, MAPK signaling pathway, Ras signaling pathway, HIF-1a signaling pathway and others." (PMID 29018223, 2017). "The miR-142/HIF-1α axis established in the present study may be essential in modulating pancreatic cancer cell growth and invasion, and may serve as a new medical portal for pancreatic cancer treatment in the future." (PMID 28069592, 2017). "Moreover, activation of β-AR receptor could up-regulate levels of HIF-1α and downstream target genes independently of oxygen level in pancreatic cancer cells." (PMID 26497365, 2016). "PAK1 may play a role in the resistance of pancreatic cancer to hypoxia through regulation of HIF1α." (PMID 26774265, 2016). "Thus, HIF-1α has a potential value to be a new therapeutic target for pancreatic cancer." (PMID 24662981, 2014). "Additionally, the inhibition of crucial HIF1a downstream target genes, which coordinate aerobic glucose consumption, may impair cell proliferation and xenograft growth in pancreatic cancer." (PMID 25103363, 2014). "Moreover, it has been reported that a novel fusicoccin derivative (ISIR-042) was more effective at inducing the growth inhibitory and cytotoxic effects on hypoxic pancreatic cancer cells than on normoxic pancreatic cancer cells in vitro and in vivo through a reduction in HIF-1α and Akt activation." (PMID 23301832, 2013). "On the other hand, it has also been shown that the activation of IGF-1/IGF-1R and SCF/KIT axes in pancreatic cancer cells may contribute to the induction of HIF-1α through the stimulation of PI3K/Akt and/or Ras/MEK/ERK pathways and tumour angiogenesis under normoxic conditions." (PMID 23301832, 2013). "Thus, we hypothesized that the EMT that pancreatic cancer cells undergo in response to HIF-1α expression occurs, at least in part, due to the HIF-1α-mediated activation of the NF-κB pathway." (PMID 21887310, 2011).